CD9 (CD9 molecule)
Diseases named in the same sentence as CD9 in open-access papers (continued):
Sharing a sentence is not in itself a finding about the gene and the disease.
breast carcinoma (continued). "The results of this study collectively suggest that miR-518f-5p is capable of modulating CD9 expression and increases non-tumorigenic breast and breast cancer cell migration in vitro and that loss of CD9 in vivo affects tumorigenesis." (PMID 32224917, 2020). "However, the majority of the literature shows a reduction in CD9 expression in breast tumors, with a more pronounced decrease with breast cancer progression, particularly in lymph node metastases." (PMID 32224917, 2020). "This suggests that CD9 can be regulated by RNA-binding proteins in breast cancer, but also that other forms of post-transcriptional regulation such as miRNAs, including miR-518f-5p, may also influence CD9 expression." (PMID 32224917, 2020). "Therefore, this study aimed to elucidate the role of miR-518f-5p and the mechanisms responsible for decreased CD9 expression in breast cancer, as well as the role of CD9 in de novo tumor formation and metastasis." (PMID 32224917, 2020). "In addition, CD9 knockdown suppressed metastatic capacity of MDA-MB-231 breast cancer cells in a mouse xenograft model, with delayed cell spreading and mesenchymal stromal cell invasion observed in vitro." (PMID 32224917, 2020). "However, very little is known about the mechanisms of regulation of CD9 expression and its dysregulation in cancers such as breast cancer." (PMID 32224917, 2020). "Therefore, CD9 appears to play a complex role in breast cancer cell functions, particularly in breast cancer cell migration and progression to metastasis." (PMID 32224917, 2020). "We have previously shown that miR-518f-5p decreases the expression of CD9 in prostate cancer, so we tested whether this was also the case in breast cancer." (PMID 32224917, 2020). "Antibodies against CD9 and CD63, which are enriched on EVs, were administrated to human breast cancer xenograft mouse models, and circulating administrated EVs tagged by anti-CD9 and -CD63 were internalized by macrophages through phagocytosis, resulting in the inhibition of cancer progression." (PMID 29534557, 2018). "Thus, we harvested exosomes from conditioned media of CT26 (colorectal cancer cell line), B16 (melanoma cell line) and 4T1 (breast cancer cell line) cells, verified they expressed CD9 and tested their ability to induce neurite outgrowth of PC12 cells." (PMID 30327461, 2018). "Investigation of CD9-targeted breast cancer therapeutic strategies is warranted." (PMID 25762645, 2015). "These novel CD9 functions could be exploited to develop innovative breast cancer therapeutic strategies." (PMID 25762645, 2015). "In support of such a hypothesis, it has been shown that the over expression of CD9 in human breast cancer promotes the development of bone metastases." (PMID 26633531, 2015). "We should also keep in mind that CD9-deficiency leads to decreased expression of ADAM10, a metalloproteinase that could play a role in breast cancer progression." (PMID 25762645, 2015). "While all of these studies pointed towards possible integrin-dependent functions for the CD9/CD81 complex in breast carcinoma cells, the specific integrins involved in each study were not defined, and, in particular, the specific contribution of α3β1 integrin was not assessed." (PMID 23613949, 2013). "Therefore, inhibition of miR-518f-5p may restore CD9 expression in breast cancers and potentially modulate cancer metastasis." (PMID 32224917, 2020). "Therefore, a mammary specific Cd9 knockout mouse model or syngeneic engrafting of Cd9−/− PyMT tumors into Cd9+/+ mice may further aid in elucidating the role of CD9 in breast cancer progression and metastasis." (PMID 32224917, 2020). "Therefore, inhibition of miR-518f-5p may restore CD9 expression and aid in the treatment of breast cancer metastasis." (PMID 32224917, 2020).
breast carcinoma (continued). "We characterizethe EV secretion of two breast cancer cell lines: triple-negativeMDA-MB-231 cells and HER2-positive SkBr3 cells secrete EVs that carrydistinguishable levels of tetraspanins (CD9, CD63, and CD81) and HSPs(−90 and −70)." (PMID 41489814, 2026). "Conversely, in plasma-enriched sEVs from stage IV breast cancer patients, HPA binding was most abundant on CD81-captured sEVs, followed by CD9, with the least binding on CD63-captured sEVs." (PMID 40411659, 2025). "HPA labelling in conjunction with ExoView analysis confirmed the co-localisation of CD63, CD81, and CD9 in both MCF-7 cell-derived sEVs and plasma-enriched sEVs derived from stage IV breast cancer patients." (PMID 40411659, 2025). "Studies have shown that defensin disrupts breast cancer cell growth and metastasis by interfering with exosomal CD63 and CD9 recruitment." (PMID 40573239, 2025). "The analysis of CD9 capture spots revealed distinct HER2 and tetraspanin expression profiles across the three breast cancer cell lines." (PMID 41226371, 2025). "Alternatively, as a prototype of pan‐EV capture, a mixture of biotinylated antibodies against human CD9 and CD81 were used to immobilise EVs from SKBR3 breast carcinoma cells onto a black streptavidin‐coated 96‐well plate." (PMID 39221546, 2024). "Just like CD9, CD63 plays a part in the regulation of breast cancer cell malignancy and the therapy resistance to tamoxifen." (PMID 36555738, 2022). "Most importantly, UEs from breast cancer patients carry more abundant key proteins (CD63, CD9, and CD47) as compared to that from normal people, which are essential for long blood circulation, immune escape and tumor targeting." (PMID 36004889, 2022). "Differential regulation of CD9 through the CD9 3′UTR was observed across the panel of non-tumorigenic and tumorigenic breast cell lines, with some breast cancer lines showing a high level of activity towards the CD9 3′UTR resulting in low protein expression." (PMID 32224917, 2020). "Antibodies against human CD9 and CD63, two well-established sEV surface markers, were shown to disrupt oncogenic sEVs and inhibit tumor metastasis in a breast cancer xenograft nude mouse model." (PMID 32847103, 2020). "However, the role of miR-518f-5p and CD9 in breast cancer is unknown." (PMID 32224917, 2020). "Several proteins interact with CLDN-1 to fuel the progression of breast cancer, including the following: Ephrin B1, ESCRT, CD9 and EpCAM." (PMID 31952355, 2020). "The common EV markers CD9, CD63 (category 1), and ALIX (category 2) were confirmed from the EVs from breast cancer cells exposed to each temperature, supporting the presence of EVs." (PMID 33408817, 2020). "Our findings suggest that within the tumor microenvironment, CD9 is responsible for the crosstalk between BMMSCs and HCC1806 breast cancer cells (via CCL5, CCR5, and CXCR12) which contributes to chemoresistance." (PMID 31191817, 2019). "There is even a synergy in simultaneous reduction of CD9 and CD82 that leads to increased metastatic potential in breast cancer." (PMID 25285080, 2014). "RNAi silencing of CD9 reduced Matrigel invasion of multiple tumor cell types, including PC-3 and 22Rv1 prostate carcinoma, and MDA-MB-231 breast carcinoma cells." (PMID 23613949, 2013). "Our data reveal that the CD9/CD81 complex and CD151 have overlapping but distinct functions in regulating α3β1-dependent behaviors in the MDA-MB-231 breast cancer model." (PMID 23613949, 2013). "We selected and validated two HuR targets, CD9 and CALM2 mRNAs, which were found in high abundance in both types of breast cancer." (PMID 20370918, 2010). "As expected, knock-down of HuR by shRNA decreased expression of CD9 and CALM2 in ER+ breast cancer (MCF-7)." (PMID 20370918, 2010).
breast carcinoma (continued). "We further characterised ultracentrifuged EVs from the different breast cancer cells by Western blot analysis, which confirmed the expression of the tetraspanin CD9 but not of calnexin, which are markers of EVs and the endoplasmic reticulum, respectively." (PMID 40524202, 2025). "We utilized SP-IRIS and CD9 bead flow cytometry assays to provide compelling evidence for the formation of HER2-positive immune complexes between trastuzumab and exosomes derived from BT474 breast cancer cells." (PMID 41226371, 2025). "Western blot analysis showed that the Luc2 mouse mammary carcinoma cells expressed CD9 and CD81 but not CD63." (PMID 39273689, 2024). "However, further mechanistic studies will be needed to clarify the role of CD9 in EMT and breast cancer progression." (PMID 37007105, 2023). "We found that CD9 protein levels were sufficient to predict a worsened outcomes in two cohorts of basal-like breast cancer patients but that CD9 mRNA in the same samples did not predict outcome." (PMID 37542044, 2023). "Additionally, it has been shown that CD9 and CD63 are present in distinct structures in human platelets as well as in mouse breast cancer cells and HeLa cells." (PMID 35524458, 2022). "The increased migration of breast cell lines following transfection of miR-518f-5p, which resulted in decreased CD9 protein expression, does not align with some of the literature on CD9 functions in breast cancer cells." (PMID 32224917, 2020). "In the current study, we observed a significant decrease in CD9 protein expression in non-tumorigenic breast and breast cancer cells following transfection of miR-518f-5p." (PMID 32224917, 2020). "This suggests that post-transcriptional regulation of CD9 by factors such as miRNA (which binds to the 3′UTR), may play an important role in breast cancer." (PMID 32224917, 2020). "Deletion of Cd9 had no obvious effect on normal mammary gland development and differentiation and did not affect mammary tumor onset or the number of tumors." (PMID 32224917, 2020). "To directly evaluate whether CD9 and HER2 molecules were co-expressed on the same EVs, we performed super-resolution microscopy (dSTORM imaging) of EVs derived from HER2+SKBR-3 compared to HER2negMDA-MB-231 breast cancer cells." (PMID 40524202, 2025). "Thus, CD9 appears to be critical for the transition from a SCLED state into treatment-resistant cell states and warrants exploration as a therapeutic target in basal-like breast cancer." (PMID 37542044, 2023). "Furthermore, Cd9−/− PyMT breast cancer mice displayed impaired tumor growth, with no significant change to pulmonary metastasis." (PMID 32224917, 2020). "Considering that treatment with anti-CD9 antibodies decreases metastasis to the lungs, lymph nodes, and thoracic cavity in TNBC, CD9 might also be a potential target of brain metastasis treatment in HER2-positive breast cancer." (PMID 32640677, 2020). "Recent findings that the CD9/CD81 tetraspanin complex regulates α3β1 integrin-dependent tumor cell behavior and that integrin α3β1 promotes breast carcinoma metastases suggests that the anti-metastatic effect observed upon CD9 knockdown could depend on the CD9 regulation of α3β1-integrin." (PMID 25762645, 2015). "Also unexpectedly, the CD9/CD81 complex, but not CD151, was required to promote α3β1 association with PKCα in breast carcinoma cells, and a PKC inhibitor mimicked aspects of the CD9/CD81-silenced cell motility defect." (PMID 23613949, 2013). "Overall, these data indicate that the ability of the CD9/CD81 complex to promote α3β1 integrin-dependent motility is not restricted to the MDA-MB-231 breast cancer model, although, unlike MDA-MB-231 cells, A431 cells also exhibit an ongoing requirement for CD151 for rapid migration on LM-332." (PMID 23613949, 2013).
breast carcinoma (continued). "However, it is not clear whether the loss of CD9 expression in breast cancer is due to differences in transcriptional or post-transcriptional regulation of CD9 in breast cancer cells compared to non-tumorigenic cells." (PMID 32224917, 2020). "In contrast, plasma-enriched HPA-positive sEVs derived from breast cancer patients with non-metastatic disease showed MFI values of 9.3, 14.8, and 14.6 for CD9 co-localisation." (PMID 40411659, 2025). "In this sense, CD9 expression and migration were induced by native type IV collagen through a DDR1-dependent pathway in the breast cancer model, but not in non-tumorigenic MCF10A and MCF12A cells." (PMID 37007105, 2023). "CD9 RNA levels did not predict outcomes in all TNBC subtypes, but were sufficient to predict a poor outcome in basal-like 2 breast cancer patients, a therapy-resistant subtype." (PMID 37542044, 2023). "In relation to our previous study on canine mammary tumor cell-derived EVs, while integrin-beta and TSG101 were not tested as EV markers, CD9 was present in both UC and SEC EVs." (PMID 37958059, 2023). "In this work, urinary exosomes (UEs) with high expression of CD9 and CD47 were extracted from breast cancer patients by a non−invasive method." (PMID 36004889, 2022). "Moreover, recent studies in breast cancer cells have shown the release of hypothetical “non-classical” exosomes generated by amphisomes (produced by fusion of multivesicular bodies -MVB- and autophagosomes)), lacking classical exosome markers (CD63, CD81, and CD9)." (PMID 38268920, 2023).
melanoma (68 papers, 2009 to 2025). A malignant, usually aggressive tumor composed of atypical, neoplastic melanocytes. "Previous studies suggested that both CD63 and CD9 were associated with promotion or inhibition of melanoma progression in cell culture models." (PMID 40521809, 2025). "Association of CD9 with transendothelial invasion has also been observed by immunohistochemistry in cervical cancer as well as in melanomas." (PMID 37007105, 2023). "CD9 could also be an important marker for SLN status, with CD9 having an increased expression in intermediate and thick melanomas, with an evident increased risk of lymph node metastasis." (PMID 36613587, 2022). "CD9, when overexpressed, enhanced melanocyte motility, suggesting that its overexpression may partly cause the invasion activity of melanoma cells across the Matrigel." (PMID 36613587, 2022). "Primary melanomas showed two variations of CD9 staining: (a) an absolute loss of reactivity in the total of thin melanomas (24/24); (b) a reactivity limited to <50% of the total intermediate and thick melanomas, occurring in 44 of the 96 lesions." (PMID 35563166, 2022). "Similarly, CD9/CD81 were shown to regulate TGF-β1 signaling in melanoma by providing critical support for TGFβR2- TGFβR1 association, which in turns favors EMT-like changes, invasion, and metastases." (PMID 29946318, 2018). "However, the reduction of CD9 caused an inhibition of melanoma cell motility whereas the transient overexpression of CD9 in human metastatic melanoma cells resulted in an increase of matrigel invasion activity." (PMID 24147081, 2013). "CAF-derived exosomes, especially those that are CD9-positive, inhibit the growth of malignant melanoma cells." (PMID 39187523, 2024). "The same group successfully reduced melanoma lung metastasis after peptide binding to tetraspanin CD9." (PMID 37007105, 2023). "Anti-CD9 monoclonal antibodies specifically inhibited the transendothelial migration of melanoma cells." (PMID 37007105, 2023). "Regarding CD9, its alterations affect extracellular vesicle secretion and mitophagy in melanoma cells." (PMID 37007105, 2023). "Our most important finding shows that the presence of CD9 hotspots is essential for melanoma cell invasion in lymphatic and endothelial vessels." (PMID 35563166, 2022). "The aim of our study was to analyze CD9 expression in melanocytic nevi and primary cutaneous melanomas through an immunohistochemistry approach to determine its correlation with melanoma invasiveness and metastatic potential." (PMID 35563166, 2022). "As shown in microphotographs of immunofluorescence and immunohistochemistry, we successfully stained CD9 positive clusters of melanoma cells, obtaining similar staining patterns with both techniques." (PMID 35563166, 2022). "As expected, CD9 expression was observed predominantly on the cytoplasm of melanoma cells in positive clusters often located in totally negative tumor areas." (PMID 35563166, 2022). "Some vitro studies on transendothelial migration of melanoma cells showed a significant role of CD9 in tumor–endothelial/lymphatic cell interaction and vascular dissemination of tumor cells." (PMID 36613587, 2022). "We showed that monovalent CD9 Fab impedes the internalization of melanoma cell-derived EVs and nuclear transfer of their cargo proteins in recipient cells." (PMID 36010551, 2022). "Cox regression analysis for MSS showed that CD9 expression, along with tumor ulceration and sentinel node status, was an independent predictor of melanoma specific survival in patients with cutaneous melanoma (p < 0.001)." (PMID 35563166, 2022). "These tumor sites with marked localized CD9 expression were detected at a density of at least three per sample in the positive intermediate and thick melanomas." (PMID 35563166, 2022). "The direct correlation between CD9 expression and distant metastasis observed in our study assesses a potential clinical value of this tetraspanin in melanoma prognosis." (PMID 35563166, 2022).